Y_RNA (Y RNA )
Gene: Miscellaneous RNA gene on chromosome 16 (86,275,429 to 86,275,523, reverse strand). Ensembl gene ENSG00000199949.
Homologues: Orthologues: macaque Y_RNA (95% identical), guinea pig Y_RNA (89% identical), guinea pig Y_RNA (87% identical), guinea pig Y_RNA (86% identical). Paralogues in human: RNY4P19 (88% identical), RNY4P14 (86% identical), RNY4P37 (86% identical), Y_RNA (86% identical), RNY4 (85% identical), RNY4P10 (85% identical), Y_RNA (85% identical), RNY4P24 (84% identical), RNY4P25 (84% identical), RNY4P6 (84% identical), RNY4P7 (84% identical), Y_RNA (84% identical), and 93 more.